CRP (C-reactive protein)
Diseases named in the same sentence as CRP in open-access papers (continued):
Sharing a sentence is not in itself a finding about the gene and the disease.
autoimmune disease (continued). "Indeed, CRP is an acute phase protein released by the liver as part of the body's immune response to nonspecific disturbances, including infection, autoimmune disorders, trauma or surgery, and cancer." (PMID 23983803, 2013). "Although there are many other conditions affecting the levels of CRP and NLR, like an infectious state and autoimmune disease, the possibility may be minimized because most of those markers were indeed tested prior to treatment, without evidence of serious infection." (PMID 23409924, 2013). "Second, while our study excluded infectious diseases, hematological disorders, and autoimmune diseases, excluded patients using drugs that affect blood counts, and corrected for the effects of C-reactive protein, we still could not eliminate the effects of some unmeasured confounders." (PMID 40153759, 2025). "Non-native CRP may serve as a tool to investigate the functions of CRP in every inflammatory disease involving deposition and aggregation of proteins, such as amyloidosis and autoimmune diseases." (PMID 31379851, 2019). "Additionally, the specificity of C-reactive protein and inflammatory cytokines (e.g. tumor necrosis factor-α and interleukin-6) for OSAS seems to be low because of the high basal levels of these substances in patients with inflammatory disease, autoimmune disease, and many other diseases." (PMID 23805411, 2013). "Erythrocyte sedimentation rate (ESR) and C-reactive protein (CRP) usually elevated in CD patients, while they are non-specific and increase in many inflammatory responses, such as infections and autoimmune diseases." (PMID 38598519, 2024). "However, none of our patients with CHD suffered from rheumatic or autoimmune diseases and only those seen in routine medical check-ups were included in the analysis, therefore, making the interference of infections or inflammatory processes with CRP measurement unlikely." (PMID 38673472, 2024). "Systemic inflammation, such as fever, elevated CRP, and ESR, is not more prominent in patients with multi-joint sJIA than single-joint sJIA, and systemic inflammation gradually evolves into an autoimmune disease phenotype." (PMID 34820342, 2021). "Despite the high levels of CRP and ESR, these patients appear to be stable without symptoms related to infection or autoimmune disease." (PMID 33122662, 2020). "The effect of marine-derived n-3 PUFAs supplementation on CRP, IL-6 and TNF-α in subjects with chronic no-autoimmune disease (data were log-transformed before analysis)." (PMID 24505395, 2014). "Cerebrospinal fluid white blood cell and protein, serum C-reactive protein and immunoglobulin G were lower in NMOSD patients without autoimmune diseases, while several autoantibodies seropositivity and thyroid indexes were significantly higher in NMOSD patients with autoimmune diseases (p < 0.05)." (PMID 25135481, 2014). "We recognize that CRP is a nonspecific marker of inflammation and can be influenced by factors beyond cancer, such as chronic obstructive pulmonary disease (COPD), bronchiectasis, autoimmune diseases, and smoking—all of which are prevalent in our patient population and particularly in men." (PMID 39590174, 2024). "In addition, unlike CRP, the PCT level is unaffected by the administration of nonsteroidal anti-inflammatory drugs (NSAIDs) or corticosteroids and by various inflammatory comorbidities (e.g., autoimmune diseases)." (PMID 34066811, 2021).
leukopenia (279 papers, 2004 to 2026). "These positive outcomes were reinforced by significant changes in diagnostic markers during her follow-up, where CRP and D-dimer values markedly reduced and her hemogram returned to normal, demonstrating the resolution of leukopenia." (PMID 39282517, 2023). "Multivariable logistic regression revealed that altered mental status, leukopenia, prolonged activated partial thromboplastin time (aPTT), and normal C-reactive protein (CRP) level (≤1.0 mg/dL) were significantly associated with SFTS." (PMID 35632834, 2022). "We showed again the important distinguishing factors of COVID-19 virus infection such as, leukopenia, the age as a risk factor for developing more severe form of the disease, and CRP and its positive correlation with lung lesions." (PMID 32668763, 2020). "Physicians should alert the appearance of skin necrosis at ER to early suspect NF and treat aggressively according to those clinical and laboratory risk indicators, such as elevated APACHE score, shock, leukopenia, higher banded leukocytes, elevated CRP, and hypoalbuminia." (PMID 37891231, 2023). "Physicians should alert the appearance of skin necrosis at ER to early suspect NF and treat aggressively by those clinical and laboratory risk indicators, such as elevated APACHE score, shock, leukopenia, higher banded leukocytes, elevated CRP, and hypoalbuminia." (PMID 37891231, 2023). "In addition, the results of certain laboratory tests (e.g., lactate dehydrogenase (LDH), >600 IU/L; hypoxemia (PaO2, <60 mm Hg); C-reactive protein (CRP), 10 mg/dl; and leukopenia <5000/mm3) have been associated with greater mortality from infection by influenza A/H1N1 virus." (PMID 23148654, 2012). "The patient also demonstrated leukopenia, elevated alkaline phosphatase level, and elevated C-reactive protein level." (PMID 39926249, 2025). "Various clinical and laboratory biomarkers such as SIRS, leukopenia, neutropenia and CRP have been introduced to predict the final outcome of dogs with CPV." (PMID 40303388, 2025). "Other clinical and laboratory markers of this entity are hemoptysis, hypotension, leukopenia, and very high serum concentrations of C-reactive protein (CRP)." (PMID 40070620, 2025). "Laboratory findings in the cases with influenza alone indicated leukopenia accompanied by normal C-reactive protein levels." (PMID 40710034, 2025). "Laboratory tests revealed leukopenia (0.46 x 10^9/L), neutropenia (0.03 x 10^9/L), a C-reactive protein (CRP) level of 284 mg/L, and a urine test result." (PMID 41523364, 2025). "Notable findings include mild leukopenia, elevated inflammatory markers (CRP, γ-GTP, CH50), and hypergammaglobulinemia (IgG)." (PMID 40761978, 2025). "Initial bloodwork revealed hemoglobin of 9.4 g/dL, leukopenia (660/μL) with neutropenia (190/μl), platelets 198 × 103/μL, and a C-reactive protein (CRP) of 0.23 mg/dL." (PMID 41321458, 2025). "Laboratory results showed leukopenia (white blood cell count: 3,000/μL; neutrophils: 54%), elevated lactate dehydrogenase (249 U/L), and increased C-reactive protein (2.36 mg/dL)." (PMID 41399553, 2025). "Observational and case–control studies have found several general inflammatory biomarkers in PANDAS/PANS, including complement activation (high C4a and low C4), leukopenia, increased C-reactive protein, Neuron-specific Enolase (NSE), and serum amyloid A (SAA)." (PMID 40869088, 2025). "In routine laboratory tests, the routine laboratory tests of some patients have not been reported, the patient’s main manifestations were elevated CRP, lymphocytes, and leukopenia." (PMID 39935681, 2025). "Laboratory tests showed leukopenia in 63/93 (68%), elevated CRP (>2.0 mg/dL) in 12/81 (15%), elevated LDH (>500 IU/L) in 17/91 (19%), and elevated sIL‐2R (>800 U/mL) in 22/77 (29%) patients." (PMID 39961627, 2025). "Blood examinations showed a slight leukopenia and C-reactive protein (CRP) level of 0.5 mg/dL, and the erythrocyte sedimentation rate (ESR) is also elevated at 47 mm/hour." (PMID 41220469, 2025).
leukopenia (continued). "Weak immune responses in children were indicated by less frequent reports of leukopenia, high CRP levels, high erythrocyte sedimentation rate, and high ALT levels." (PMID 40283407, 2025). "All three children had thrombocytosis, while the two with leucocytosis had CRP levels of 51 and 128 (Case 4 and Case 7), respectively, and the one with leukopenia had a CRP level of 39 (Case 1)." (PMID 40336439, 2025). "Laboratory tests revealed acute, profound leukopenia and elevated C-reactive protein (CRP) and procalcitonin (PCT) levels." (PMID 39728022, 2024). "Leukopenia and elevated CRP were the most observed grade 3 adverse effects, with 15.6% and 10.1%, respectively." (PMID 38877146, 2024). "Blood tests at admission showed leukopenia (WBCs, 3740/μL) and elevated inflammatory markers (CRP, 288.8 mg/L)." (PMID 39061349, 2024). "Laboratory workup showed leukopenia in 66% and increased C-reactive protein (CRP) levels in 63% of cases." (PMID 38413992, 2024). "The unexpected AEs consist of PTs such as leukopenia, elevated C-reactive protein levels, tachycardia, bradycardia, salivary hypersecretion, hyperkalemia, among others." (PMID 39840097, 2024). "Blood tests showed leukopenia (white blood cells WBCs, 1910/μL; normal value, 5000–195,000/μL), slight elevation of CRP levels (8.2 mg/L), and elevated procalcitonin (PCT, 8.93 ng/mL; normal value < 0.5 ng/mL)." (PMID 39061349, 2024). "Laboratory findings, including reduced CRP and D-dimer values, and a normal hemogram on discharge indicated a resolution of leukopenia." (PMID 39282517, 2023). "The skin necrosis group had a significantly higher incidence of APACHE score, postoperative intubation, Intensive care unit stay, septic shock, leukopenia, higher counts of banded leukocytes, elevated C-reactive protein (CRP), and lower serum albumin level." (PMID 37891231, 2023). "Clinically, the infection of influenza A/H3N2 was more severe than A/H1N1 or B in terms of fever, leukopenia, and C-reactive protein." (PMID 37240745, 2023). "Given that the symptoms of COVID-19 infection are similar to those of a disease flare-up, it is difficult to distinguish between the two, especially since both can present elevated erythrocyte sedimentation rate (ESR), C-reactive protein (CRP) and leukopenia." (PMID 37675163, 2023). "The follow-up diagnostic information in this case, including the significant reduction in CRP and D-dimer values and the return to normal hemogram, indicates the resolution of leukopenia and demonstrates the effectiveness of the treatment." (PMID 39282517, 2023). "Laboratory tests revealed leukopenia (2.8 × 103/μL), elevated C-reactive protein levels (0.46 mg/dL), and the presence of antinuclear antibodies (ANA) and anti-Sjögren's syndrome-related antigen A antibodies." (PMID 37965419, 2023). "Regarding the evaluation of laboratory findings, the literature presented the follow-up of LD-P, D_Dimer, Ferritin, CRP, LD-P, γGT, and in some patients the presence of leukopenia." (PMID 36143919, 2022). "The following variables were analyzed in terms of C-reactive protein levels and leukopenia episodes: sex, age, diagnosis of inflammatory bowel disease and type of drug." (PMID 35584442, 2022). "This study identified four new parameters for predicting SFTS considering all the study models: leukopenia, prolonged aPTT, normal CRP level (≤3.0 mg/dL), and elevated CK level (> 1000 IU/L)." (PMID 35632834, 2022). "After logistic regression, altered mental status (OR 15.385, p = 0.006), leukopenia (OR 92.573, p ≤ 0.001), prolonged aPTT (OR 65.010, p ≤ 0.001), and normal CRP level (≤3.0." (PMID 35632834, 2022). "Presence of leucocytosis or leukopenia, elevated neutrophil count, elevated C‐reactive protein (CRP), decreased eGFR, increased urea, increased alkaline phosphatase (ALP), decreased albumin, and increased sodium were associated with 28 day mortality." (PMID 35257497, 2022).
leukopenia (continued). "Our scoring system that incorporated leukopenia, prolonged aPTT, normal CRP level (≤3.0 mg/dL), and elevated CK level (>1000 IU/L) easily differentiated SFTS from scrub typhus in an endemic area." (PMID 35632834, 2022). "More patients had mucocutaneous and musculoskeletal involvements, leukopenia, increased C-reactive protein, anti-dsDNA antibody positive, and hypocomplementemia at admission and were treated with methotrexate and leflunomide during hospitalization." (PMID 35849245, 2022). "TEAEs most frequently reported by subjects administered matching placebo included lymphocytopenia (100%), leukopenia (50.0%), elevated C-reactive protein (100%), neutropenia (50%), fever (100%), headache (100%), and myalgia (50%)." (PMID 34489712, 2021). "Leukopenia, impairments in liver and muscle enzymes, abnormal C-reactive protein, ferritin and d-dimer levels were the important biochemical tests." (PMID 33731172, 2021). "TEAEs most frequently reported by subjects administered 60 mg HEC30654 included lymphocytopenia, leukopenia, elevated C-reactive protein, neutropenia, fever, headache, and myalgia." (PMID 34489712, 2021). "Six patients had leukopenia, 17 had elevated C-reactive protein (CRP), and 8 had lymphocytopenia and elevated lactate dehydrogenase (LDH)." (PMID 38630071, 2021). "The pooled prevalence of leukopenia was 7.3% (95% CI: 3.4%–12.2%), and the C-reactive protein level was high in 14.0% (95% CI: 6.8%–22.8%)." (PMID 33847620, 2021). "TEAEs most frequently reported by subjects administered 60 mg HEC30654 included lymphocytopenia (100%), leukopenia (87.5%), elevated C-reactive protein (75.0%), neutropenia (62.5%), fever (100%), headache (75.0%), and myalgia (75.0%)." (PMID 34489712, 2021). "Overall, leukopenia was observed in 19 (38%) patients and elevated C-reactive protein in ten (20%) patients." (PMID 32370747, 2020). "These laboratory values are high D-dimer (p<0.001), C-reactive protein (p<0.001), procalcitonin (p<0.001), and leukopenia (p<0.014)." (PMID 33206816, 2020). "In contrast, for the 130 patients in the febrile cohort, 73.8% of evaluations were distributed between D1 and D4 after the onset of illness, and 68.8% of patients had the S2 subtype of ‘leukopenia plus normal CRP’." (PMID 32134948, 2020). "In our study, the most frequently reported laboratory findings was lymphocytopenia (66.1%), followed by elevated C-reactive protein marker (56.6%), leukopenia (48.3%) and elevated lactate dehydrogenase (34.8%)." (PMID 32887660, 2020). "The period of D1 to D4 was the most frequently visited, which included 73.8% (96/130) of patients; the S2 subtype of ‘leukopenia plus normal CRP’ was the main presentation, including 68.8% (66/96) of patients." (PMID 32134948, 2020). "A separate study developed an SFTS differentiation score based on four parameters; altered mental status, leukopenia, prolonged aPTT, and a normal CRP level." (PMID 33374620, 2020). "Among the febrile cases presenting with S2, the predominant subtype was ‘leukopenia plus low CRP’ (68.8%), and the temporal distribution of S2 and S3 was narrow, mostly distributed within day 4 (D4)." (PMID 32134948, 2020). "On admission, leukopenia was present in 16.0% of the patients, lymphocytopenia in 12.0%, and elevated levels of CRP in 60.0%." (PMID 33009366, 2020). "The results showed that enlarged liver, spleen and lymph nodes, digestive system involvement, low hemoglobin, leukopenia, CRP, decreased albumin, anti-dsDNA antibody, glucocorticoids, and cyclophosphamide were associated with noninfectious fever in SLE." (PMID 30847312, 2019). "One study previously proposed a similar scoring system using 4 variables: altered mental status, leukopenia, prolonged activated partial thromboplastin time and normal C-reactive protein." (PMID 30782137, 2019).
leukopenia (continued). "Factors, such as enlarged liver, spleen and lymph nodes, digestive system involvement, low hemoglobin, leukopenia, CRP, decreased albumin, anti-dsDNA antibody, glucocorticoids, and cyclophosphamide, were independent risk factors for noninfectious fever in SLE." (PMID 30847312, 2019). "The following factors were closely associated with fever: patient age, treatment history, SLEDAI score, enlarged liver, spleen and lymph nodes, low hemoglobin, leukopenia, CRP, complement C3, albumin, anti-dsDNA antibody, glucocorticoids, and cyclophosphamide." (PMID 30847312, 2019). "Peripheral leukopenia and metabolic acidosis were also detected, and serum CRP level was elevated to 70.6 mg/L." (PMID 25625669, 2015). "In seasonal influenza, cough, mild leukopenia, and mild C-reactive protein elevation are relatively common clinical manifestations." (PMID 22022474, 2011). "Blood examination data indicated leukopenia (white blood cell count, 2500 cells/μL), and a high C-reactive protein (CRP) level (16.7 mg/dL)." (PMID 19811627, 2009). "The temporal correlation between chemotherapy administration and the onset of symptoms, coupled with the presence of chemotherapy-induced leukopenia and systemic inflammation (elevated CRP), further supports the role of chemotherapy in the development of the dissection." (PMID 41332067, 2025). "Blood test showed leukopenia in 66% and increased C-reactive protein (CRP) levels in 63% of cases." (PMID 38413992, 2024). "He presented to the Emergency Department (ED) of S. Jacopo Hospital in Pistoia, Italy, after about 3 weeks of fever and a history of about five kg weight loss; the results of a chest X-ray (CXR) were normal, and blood tests (BTs) evidenced mild leukopenia and increased C-reactive protein (CRP)." (PMID 39195009, 2024). "Of note, most of these associations remained unaffected by adjustment for age and sex: presence of leucocytosis/leukopenia, increased neutrophil count, elevated CRP, decreased eGFR, elevated urea, decreased albumin, and elevated sodium retained their association with 28 day mortality." (PMID 35257497, 2022). "Therefore, we can easily differentiate SFTS from scrub typhus in endemic areas using a scoring system incorporating leukopenia, aPTT prolongation, normal CRP level, and elevated CK level." (PMID 35632834, 2022). "After logistic regression, leukopenia (OR 145.404, p ≤ 0.001), prolonged aPTT (OR 250.124, p ≤ 0.001), normal CRP level (OR 172.021, p ≤ 0.001), and elevated CK level (OR 192.616, p = 0.001) were significantly associated with SFTS compared to scrub typhus (Model C)." (PMID 35632834, 2022). "Lactate dehydrogenase, and C-reactive protein peaked earlier than procalcitonin and leukopenia." (PMID 33767213, 2021). "These factors include leukopenia, elevated CRP, or ESR, and liver enzymes." (PMID 33425269, 2020). "Abnormal laboratory tests included leukopenia (n=7, 18%), lymphocytopenia (14, 35%), increased alanine aminotransferase (9, 23%), aspartate aminotransferase (5, 13%), lactate dehydrogenase (5, 13%), C-reactive protein (19, 48%) and D-dimer (7, 27%)." (PMID 33162792, 2020). "Among the most commonly reported laboratory findings, lymphocytopenia was the most frequently reported in the three coronavirus infections with prevalence ranged from 63 to 100%, followed by elevated C-reactive protein and leukopenia with prevalence ranged from 45 to 100%." (PMID 32887660, 2020). "In addition, her confused mental state, soft tissue infection following DIC with high inflammatory status (CRP 23.8 mg/dL; procalcitonin 8.37 ng/mL) and extreme leukopenia (900/μL) all suggested severe infection and toxicity." (PMID 28705211, 2017). "Because hepatocytes are the primary source of CRP, we did not anticipate a greater incidence of falsely negative CRP in VLBWs with leukopenia but previous studies suggested this association." (PMID 24244325, 2013).